CAT (catalase)
Diseases named in the same sentence as CAT in open-access papers (continued):
Sharing a sentence is not in itself a finding about the gene and the disease.
malaria (26 papers, 2010 to 2025). Malaria is a serious and sometimes fatal disease caused by a parasite that commonly infects a certain type of mosquito which feeds on humans. "The association between catalase and other antioxidant systems in malaria is complex and interconnected." (PMID 37670044, 2023). "Understanding the variations in CAT levels in the context of malaria infection can offer insights to improve the diagnostic, therapeutic, and preventive strategies for malaria, particularly concerning the unique needs and vulnerabilities of pregnant women." (PMID 37670044, 2023). "At the lowest dose of the extract (125 mg/kg), a significant boost in catalase activity was noted as 56.52% (p < 0.01) in the kidneys and 52.94% in the brain related to malaria control." (PMID 41446556, 2025). "Studies have shown that the primary defenses against oxidative stress, such as SOD, catalase, and glutathione peroxidase, are decreased in patients with malaria, indicating a compromised endogenous antioxidant system." (PMID 38926807, 2024). "In contrast, a couple of studies reported higher CAT levels in individuals with malaria compared with the uninfected controls." (PMID 37670044, 2023). "CAT levels were higher in malaria-infected individuals compared with uninfected controls in three studies." (PMID 37670044, 2023). "Eleutherin and isoeleutherine were the ones that presented the lowest binding energy for CAT, GR, and GPx1, showing themselves to be possible targets of these molecules in the involvement of the redox balance during malaria." (PMID 37513429, 2023). "Inconsistent catalase (CAT) research necessitates a comprehensive review of CAT levels among patients with malaria to achieve better therapeutic strategies." (PMID 37670044, 2023). "Following PRISMA guidelines, a systematic literature search across six databases was conducted to examine CAT levels in patients with malaria." (PMID 37670044, 2023). "Upon excluding the results of these particular studies and rerunning the meta-analysis, a significant decrease in CAT levels among patients with malaria compared with those in uninfected controls was observed (P < 0.05)." (PMID 37670044, 2023). "In studies involving nonpregnant individuals, the levels of CAT were consistently lower in individuals infected with malaria compared with uninfected controls." (PMID 37670044, 2023). "In summary, among nonpregnant individuals, the available evidence suggests that CAT levels were generally lower in malaria-infected individuals compared with uninfected controls, although certain studies reported higher CAT levels in infected individuals." (PMID 37670044, 2023). "Identifying and controlling for potential confounding factors can help in understanding the direct relationship between CAT levels and malaria." (PMID 37670044, 2023). "Among the studies that focused on nonpregnant individuals, a consistent finding was observed, with CAT levels being lower in individuals with malaria compared with uninfected controls." (PMID 37670044, 2023). "It revealed a significant decrease in CAT levels among malaria cases compared with those in uninfected controls [Hedges’ g: − 0.98, 95% CI: − 1.07–(− 0.89)]." (PMID 37670044, 2023). "The present study investigated the levels of CAT in those infected with malaria compared with the uninfected controls." (PMID 37670044, 2023). "This emphasizes the need to obtain a comprehensive overview of CAT dynamics in the context of malaria." (PMID 37670044, 2023). "Malaria parasites lack catalase and glutathione peroxidase and therefore depend on their other glutathione and thioredoxin-dependent redox relays." (PMID 35434650, 2022). "Inhibiting catalase offers multiple ways of preventing malaria transmission, by resulting in the death of the mosquito or by supporting parasite clearance in the mosquito." (PMID 32912275, 2020).
malaria (continued). "Conversely, mean levels of GSH (P < 0.0001), GPx (P < 0.0001) and CAT (P < 0.0001) were significantly higher in the healthy control group than in the malaria group." (PMID 31288760, 2019). "By contrast, mean levels of GPx (P < 0.0001) and CAT (P = 0.0022) were significantly higher in SCD control group than SCD malaria." (PMID 31288760, 2019). "In this study there is a significant decrease in catalase activity in the malaria positive isolates compared to controls which is in total agreement with them." (PMID 31288760, 2019). "However, in contrast to these findings, some studies reported higher CAT levels in malaria-infected individuals compared with uninfected controls." (PMID 37670044, 2023). "However, the current landscape of research on CAT levels in patients with malaria reveals inconsistencies and gaps, particularly concerning specific demographics like pregnant and nonpregnant individuals and spanning different disease severities." (PMID 37670044, 2023). "A possible explanation for the observed significant difference in CAT levels of the studies that used microscopy alone as the method for diagnosing the presence of malaria parasites is the fact that microscopy is a standard method for identifying such parasites." (PMID 37670044, 2023). "Additionally, the meta-analysis focusing specifically on children showed a significant decrease in CAT levels in malaria cases compared with that in the uninfected controls." (PMID 37670044, 2023). "These divergent findings may indicate variations in the study populations, methodology, or other factors that influence CAT levels in the context of malaria." (PMID 37670044, 2023). "Several studies investigating the relationship between MDA and the antioxidant system in the context of malaria showed that the activities of various antioxidant enzymes, such as superoxide dismutase (SOD), glutathione peroxidase, and catalase, were decreased during malaria." (PMID 37627497, 2023). "Thus, evaluating CAT levels in patients with malaria not only provides deeper insights into its impact on oxidative stress but also carries broader therapeutic implications for both malaria and associated conditions like bacterial infections." (PMID 37670044, 2023). "Similarly, the subgroup analysis that used microscopy alone as the method for diagnosing the presence of malaria parasites also showed a significant decrease in CAT levels in malaria cases compared with that in the uninfected controls." (PMID 37670044, 2023). "Notably, among studies conducted in Africa, a significant difference in CAT levels was observed between malaria cases and uninfected controls." (PMID 37670044, 2023). "Importantly, malaria patients have been reported to have lower catalase activity than healthy controls, but a higher SOD activity, thus resulting in the accumulation of H2O2." (PMID 33467515, 2021). "The difference in the minimal amount of H2O2 required to fully oxidize HyPer-3 and roGFP2-Orp1 in vitro (20 μM and 5 μM, respectively) and in living malaria parasites (1 mM) is likely due to the antioxidant capacity of the parasite-host cell unit including catalase and peroxiredoxins." (PMID 28369083, 2017). "The glutathione and thioredoxin systems may provide a way for malaria parasites to maintain redox homeostasis and antioxidant defense, considering that P. falciparum lacks glutathione peroxidase and catalase." (PMID 29128848, 2017). "Finally, malondialdehyde plasma levels (a marker of lipid oxidation) or urinary F2-isoprostane (marker of oxidative stress) are increased in malaria patients, while antioxidant levels (e.g. ascorbate, α-tocopherol, catalase) are suppressed." (PMID 24586264, 2014). "Considering several previous reports demonstrating the role of antioxidant enzymes, including catalase, in the response of A. gambiae to the murine malaria parasite P. berghei, we investigated the effect of catalase silencing in A. aquasalis response to P.vivax." (PMID 23441231, 2013).
malaria (continued). "Indeed, it has been described that both glutathione and catalase might be reduced during severe malaria and high levels of SOD-1 could lead to the exacerbation of the oxidative stress and inflammation, aggravating the outcome of the disease." (PMID 23433077, 2013). "In this regard, anti-malarial drug therapy for malaria patients reduces lipid peroxide levels, which results in significant restoration of antioxidant status, including GSH, SOD, catalase, and GPx levels." (PMID 37626133, 2023). "The reasons for exclusion were as follows: 789 records were not related to malaria, 223 records were not related to catalase, and 28 records had no abstract." (PMID 37670044, 2023). "Results of qualitative synthesis among nonpregnant individuals consistently showed lower CAT levels in malaria-infected individuals, although some studies reported higher levels." (PMID 37670044, 2023). "In all three studies, there was no observed difference in CAT levels between severe and nonsevere malaria cases." (PMID 37670044, 2023). "However, the accumulation of H2O2 due to the decrease in CAT and GSH-Px activities in patients with malaria can inactivate SOD activity, which catalyzes the conversion of O2•− into H2O2." (PMID 35682626, 2022). "The mean level of CAT was also higher in malaria group than SCD malaria group, but the difference was not statistically significant (P = 0.3085)." (PMID 31288760, 2019). "Oxidative stress markers such as malondialdehyde levels in persons with malaria are higher, compared to the uninfected ones, while catalase activities are lower in those with malaria than those without the disease." (PMID 31360173, 2019). "In this study, the difference in the levels of SOD, GSH, CAT and NO between malaria non infected and infected women was not significant, although the levels of MDA increased with malaria infection." (PMID 26267795, 2015). "Since malaria parasites do not possess catalase and genuine GSH peroxidase in their genome, it is considered that GSH itself is the major redox buffer for transient H2O2 exposure and the basal peroxide flux in the cell is dealt with by the Trx system." (PMID 23146411, 2012). "Furthermore, three studies that compared the differences in CAT levels across various levels of clinical malaria demonstrated no observed difference in CAT levels between severe and nonsevere malaria cases." (PMID 37670044, 2023). "This study aimed to systematically review and meta-analyze available literature on CAT levels in nonpregnant and pregnant individuals with malaria compared with those in uninfected controls, with the goal of providing a robust evidence base for future research and potential interventions." (PMID 37670044, 2023). "Furthermore, it is worth noting that some studies did not observe any significant difference in CAT levels between malaria-infected individuals and the uninfected controls." (PMID 37670044, 2023). "One could speculate that malaria, by modulating CAT levels, could heighten the vulnerability of individuals, notably children, to secondary bacterial infections due to a weakened antioxidant defense mechanism." (PMID 37670044, 2023). "Among the studies that enrolled nonpregnant individuals and reported quantitative data of CAT levels between malaria and uninfected controls, the results of eight individual studies showed that CAT levels were lower in malaria-infected individuals compared with uninfected controls." (PMID 37670044, 2023). "Interestingly, among the nonpregnant individuals, CAT levels were found to be lower in severe malaria cases compared with the controls." (PMID 37670044, 2023). "Reduced catalase activity together with increased SOD activity may result in the accumulation of H2O2, the release of hydroxyl radicals and increased tissue damage during severe malaria." (PMID 20386593, 2010).
malaria (continued). "The biomarkers namely: malondialdehyde (MDA), reduced glutathione (GSH), catalase (CAT) and glutathione peroxidase (GPx) were determined in plasma samples from SCD malaria positive, malaria positive, SCD malaria negative and healthy control participants." (PMID 31288760, 2019). "The levels of MDA, GSH, CAT, SOD and NO were measured in teased placenta tissue supernatants of malaria infected and non-infected women at delivery." (PMID 26267795, 2015).
acatalasemia (24 papers, 2010 to 2025). "Catalase is also widely used in clinical studies as it is an antioxidant enzyme, and catalase deficiency has been associated with several diseases, such as acatalasemia, vitiligo, coronary artery disease, cancer, and type 2 diabetes." (PMID 39015602, 2024). "Homozygous pathogenic CAT variants are associated with the rare condition acatalasemia, also known as acatalasia, which leads to total or near total loss of CAT activity in erythrocytes." (PMID 38397443, 2024). "Acatalasemia, an autosomal recessive disorder, characterized by oral ulcers, is also caused by significantly reduced levels of CAT." (PMID 37839702, 2023). "Many allelic variants of CAT have been documented, with the first described form of acatalasemia tracing back to a splicing mutation prevalent in the Japanese population." (PMID 37109666, 2023). "Acatalasia (acatalasemia or Takahara disease) is an inherited autosomal disorder caused by the absence or very low levels of the enzyme catalase caused by a mutation in the CAT gene." (PMID 35329073, 2022). "Acatalasemia in humans is considered an asymptomatic disease, and catalase-deficient mice are described as being phenotypically normal." (PMID 35480487, 2022). "Acatalasemia is a rare genetic deficiency in humans that involves severe reductions in catalase activity and is usually an autosomal recessive inheritance." (PMID 35480487, 2022). "The catalase variant was reported as causative for acatalasemia/hypocatalasemia (OMIM 614097) in a study that found a reduction in catalase levels in patients carrying the variant." (PMID 35743704, 2022). "In contrast, individuals with a genetic predisposition for low catalase activity (e.g., acatalasemia, catalase mutations) are at higher risk of T2D." (PMID 33921645, 2021). "Acatalasemia refers to a genetic deficiency in erythrocyte catalase activity that increases H2O2 concentration in tissues, as glutathione peroxidase activity does not compensate for the lack of catalase." (PMID 33080438, 2020). "Acatalasemia (AC) is a hereditary disorder which is linked with the anomaly of catalase enzyme affecting its activity." (PMID 31827713, 2019). "Two kinds of mutations in the catalase gene have been reported to be involved in the Japanese acatalasemia." (PMID 31827713, 2019). "The study on the fibroblast from Swiss acatalasemia patients suggests that structural mutations in the CAT gene are responsible for inactivation of catalase." (PMID 31827713, 2019). "The frequency of various CAT mutations has been found to be increased in individuals with DM, especially in females with type 2 DM, and such inherited catalase deficiency is associated with an early onset of type 2 DM." (PMID 29113320, 2017). "Acatalasemia, the deficiency of catalase enzyme activity associated with a CAT gene variant (c.979G>A), was originally characterized in research colonies of Beagles." (PMID 27525650, 2016). "Polymorphisms in this gene have been associated with decreases in catalase activity but, to date, acatalasemia is the only disease known to be caused by this gene." (PMID 23961996, 2013). "Genetic defects of catalase were first documented by Takahara in Japanese patients who exhibited a deficiency of blood catalase enzyme activity (acatalasemia)." (PMID 22443450, 2012). "Inherited catalase deficiency results in acatalasemia (homozygous state) and hypocatalasemia (heterozygous) and is related to increased plasma homocysteine concentrations." (PMID 21138591, 2010). "For example, acatalasemia/hypocatalasemia prevalence has been estimated at over 2% in some Asian populations, making it important to consider individual ancestry when interpreting catalase variants." (PMID 35743704, 2022). "Deficiency of catalase (acatalasemia) may result in elevation of HP concentration and favour oxidative stress and contribute to late onset disorder such as DM." (PMID 25243114, 2014).
acatalasemia (continued). "The heterozygote of acatalasemia shows half of the catalase activity than normal and this phenotype is known as hypocatalasemia." (PMID 31827713, 2019). "Studies at his laboratory led Goth to suggest that mutations of the CAT gene and resultant structural changes in the catalase protein are responsible for Hungarian acatalasemia." (PMID 31827713, 2019). "It has been reported that an anomaly of catalase activity is inherited in acatalasemia which is a rare genetic disorder (also known as Takahara disease)." (PMID 31827713, 2019). "Acatalasemia is a syndrome marked by a genetic deficiency of catalase, and there are no studies on migraine prevalence in acatalasemia." (PMID 40724883, 2025). "In acatalasemia, CAT activity is almost completely lost, leading to oxidative stress damage." (PMID 41462637, 2025). "Although splicing variants of Catalase gene are not commonly found in wildtype subjects, mutation of the CDS or splicing junctions do create nonsense/missense mutations of Catalase, which causes a disease called acatalasia/acatalasemia in humans." (PMID 37569637, 2023).